EGFR (epidermal growth factor receptor)
Diseases named in the same sentence as EGFR in open-access papers (continued):
Sharing a sentence is not in itself a finding about the gene and the disease.
metastasis (58 papers, 2011 to 2026). The spread or migration of cancer cells from one part of the body (where they first appeared) to another. "EGFR-mutated NSCLC leads to brain metastasis in about 50%–60% of patients, so finding an agent with CNS activity is vital." (PMID 38107063, 2023). "In summary, our study revealed that gefitinib treatment for patients with NSCLC harboring EGFR-TKIs sensitizing mutation causes osteosclerotic changes of lytic or mixed bone metastasis in 98% of patients." (PMID 36581856, 2022). "These 182 patients with contra-lateral lung metastasis harboring EGFR mutation under first-line TKI prescription were admitted for assessing TD-TKI, PFS and OS." (PMID 36307507, 2022). "In conclusion, miliary lung metastasis of NSCLC represented higher rate of extra-pulmonary metastasis and EGFR mutation." (PMID 36307507, 2022). "It is also likely that other factors, such as sex, age, smoking status, PD-L1 expression, CNS or liver metastasis, and EGFR or RAS mutation, influenced the efficacy of anti-PD-1/PD-L1 inhibitors in all trials." (PMID 32034198, 2020). "Our study confirmed that icotinib is as efficacious as gefitinib for brain metastasis of advanced NSCLC with EGFR mutation." (PMID 32000711, 2020). "The expression of CK7 and ELF3 in tumor tissues and EGFR in PBMCs was associated with lymph node metastasis (all p < 0.05)." (PMID 27827952, 2016). "On the contrary, in a publication studying association between oncogenes and patterns of metastatic spread 40, 10 among 39 patients with EGFR-mutated tumors had liver metastasis." (PMID 24408092, 2014). "The presence of abdominal metastasis was independently associated with early progression in metastatic NSCLC receiving EGFR-TKI." (PMID 24408092, 2014). "In our study, liver metastasis was linked to the worst prognosis, with median overall survival of 14 months, aligning with previous evidence showing that liver involvement is an adverse prognostic factor in EGFR-mutant NSCLC." (PMID 40870512, 2025). "Notably, bone metastasis was significantly more common in cases with EGFR exon 19 mutations (p = 0.016)." (PMID 40870512, 2025). "The relationship between the presence of liver metastasis in patients with EGFR‐mutated NSCLC and the prognostic outcome of osimertinib remains unclear and requires further investigation." (PMID 37548381, 2023). "When comparing patients with an OS >12 months to those with OS ≥12 months, younger age, adenocarcinoma subtype, the presence of an EGFR mutation, and contralateral lung metastasis were associated with longer OS (p-value 0.014, <0.01, 0.02, and 0.019, respectively)." (PMID 37771447, 2023). "Amplification and overdose of epidermal growth factor receptor (EGFR) were identified in several brain metastatic solid tumors, indicating that EGFR mutations and amplification are involved in the tumorigenesis of brain metastasis." (PMID 23443093, 2012). "In gastric cancer liver metastasis, TDEs deliver membrane EGFR to liver stromal cells prior to liver metastasis." (PMID 34109113, 2021). "Of note, our findings also suggest that the presence of a larger (>6 mm) discrete lung metastasis is inversely correlated with diffuse lung metastases in the setting of EGFR-mutant NSCLC." (PMID 31540242, 2019). "Our results indicate that EGFR and CCND1 CNAs are significantly associated with clinical stage, tumor differentiation, and lymph node metastasis." (PMID 31159251, 2019). "AZD3759 is a potent CNS-penetrant EGFR TKI currently being evaluated along with osimertinib in a phase 1 (BLOOM) study (NCT02228369) in patients with progressive CNS metastasis who have already had first-line treatment with EGFR TKI." (PMID 27938382, 2016). "A 73-year-old male with sigmoid colon cancer and synchronous lung metastasis was treated with panitumumab, an alone anti-EGFR monoclonal antibody as the third-line therapy." (PMID 24517087, 2014).
metastasis (continued). "Other authors reported that epidermal growth factor receptor pathway was up-regulated in metachronous liver metastasis while angiogenesis was up-regulated in synchronous liver metastasis." (PMID 22712570, 2012). "In conclusions, this retrospective study suggests that for the patients, treated with EGFR‐TKIs ≥6 months, EGFR exon 19 del, osteogenic bone metastasis, bisphosphonate application times ≥6, smoking <400/day and the number of BM <3 were predictors of better OS (p < .05)." (PMID 35614541, 2023). "The prevalence of CNS metastasis in patients with specific genomic alterations was the following: ALK (34.9%), RET (32.2%), KRAS (30.2%), EGFR (29.4%), and wild type (28.8%)." (PMID 40423053, 2025). "Factors at the 0.10 level in the univariate analysis (TNM stage, tumor differentiation, tumor size, Resection margins, lymph node metastasis, AREG expression and AREG/EGFR co-expression) were entered into a multivariate survival analysis." (PMID 27391842, 2016). "Negative correlations were found between miR-193a-3p and tumor size (r = −0.277, P = 0.002), lymph node metastasis (LNM) (r = −0.186, P = 0.038), TNM (r = −0.226, P = 0.011), EGFR protein expression (r = −0.272, P = 0.041)." (PMID 26257582, 2015). "Compared to EGFR+ or EGFR−/ALK− tumors, ALK+ tumors are more strongly associated with the absence of pulmonary metastasis and the presence of lymphangitic carcinomatosis, distant lymph node metastasis, and sclerotic bone metastasis." (PMID 40299864, 2025). "This incidence is similar to that seen among EGFR wild-type NSCLC, suggesting EGFR mutations do not confer a higher risk for developing liver metastasis." (PMID 36765587, 2023). "Addition of immunotherapy to anlotinib may prolong PFS in patients with adenocarcinoma, wild-type EGFR, stage IV disease, no liver metastasis, exsmoker status, two or more previous treatment lines, and no previous VEGF or EGFR target therapies." (PMID 34395243, 2021).
multiple myeloma (58 papers, 2010 to 2025). "Moreover, development of resistance to EGFR TKIs has been shown to cause decreased mitochondrial respiration and increased glycolysis in myeloma cells, indicating that EGFR TKI indeed is affecting the metabolic signature in cells." (PMID 33668151, 2021). "Multiple myeloma (MM) was characterized by frequent mutations in KRAS/NRAS/BRAF within the EGFR pathway that could induce resistance to EGFR inhibitors." (PMID 25894462, 2015). "In primary multiple myeloma cells and RPMI8226 cells, ALCAM associates with inactive ligand-free EGFR." (PMID 39594667, 2024). "This study went on to show how the EGFR inhibitor erlotinib demonstrated anti-tumor activity by inhibiting receptor-mediated angiogenesis in multiple myeloma in xenograft mouse models." (PMID 39272790, 2024). "Amphiregulin (AREG) in multiple myeloma-derived exosomes results in the activation of epidermal growth factor receptor (EGFR) ligand in pre-osteoclasts and is involved in multiple myeloma-induced osteoclastogenesis." (PMID 36678850, 2023). "The new insights provided by our study warrant further investigation of the clinical potential of tyrosine kinase inhibitors of EGFR/ERBB1 in treatment of multiple myeloma." (PMID 36311273, 2022). "This has included clinical evaluation of CAR-T cells directed against CD19 and CD22 for B-lymphoblastic leukemia, BCMA and CD19 for multiple myeloma, and EGFR and CD133 for cholangiocarcinoma." (PMID 36531912, 2022). "More specifically, laminin 8 serves as a connector between integrin 6 and EGFR, thereby enables the interaction between myeloma cells and MSCs." (PMID 34150666, 2021). "To determine the functional role of MSC EGFR in myeloma-induced bone cell differentiation, we first cocultured MSCs and myeloma cells with the EGFR neutralizing antibody, washed out the antibody, and collected the CM." (PMID 34150666, 2021). "Distinct from other integrins, myeloma cell α6 forms a trimer complex with laminin 8 and EGFR on MSCs, and the complex enhances osteolytic cytokine production through α6-mediated signaling pathways in myeloma cells and through EGFR-mediated signaling in MSCs." (PMID 34150666, 2021). "For example, cetuximab, a monoclonal antibody against epidermal growth factor receptor (EGFR) inhibitor generated in a mouse myeloma cell line SP2/0 was associated with development of ADA owing to its glycosylation profile." (PMID 32477334, 2020). "We anticipate that anti-CD27 can be used to enhance the effects of other direct-targeting mAbs such as anti-CD38 in myeloma and anti-EGFR in solid tumors, and we are in the process of investigating this." (PMID 29198913, 2017). "First, decorin confers direct anti-myeloma effects by binding to several receptors on the MCs, such as Met, EGFR, and IGF-IR, which consequently degrades the receptors and downregulates downstream signaling, thereby inhibiting cell growth." (PMID 26379028, 2015). "We therefore tended to study the metabolic shift in myeloma cells with KRAS/NRAS/BRAF WT background in response to EGFR inhibition, which was expected to confer primary efficacy." (PMID 25894462, 2015). "Interestingly, combination therapy with melphalan and an EGFR inhibitor resulted in a reduction of the SP and a significantly lower disease burden in 5TGM1 myeloma bearing mice compared to monotherapies." (PMID 37744361, 2023). "Interestingly, multiple myeloma patients with the highest EGFR/ERBB1 expression had worse survival outcomes." (PMID 36311273, 2022). "Our results show that myeloma cell integrin α6 binds to laminin 8 and epidermal growth factor receptor (EGFR) on MSCs, forms a trimer complex, activates the ERK1/2, STAT1/3, PI3K/Akt signaling pathways, enhances the secretion of osteolytic cytokines from myeloma cells and MSCs." (PMID 34150666, 2021).
multiple myeloma (continued). "Integrin α6 binds to laminin 8 and epidermal growth factor receptor on mesenchymal stem cells (MSCs) to form a trimer complex and upregulates the secretion of osteolytic cytokines from both myeloma cells and MSCs, leading to enhanced bone resorption and reduced bone formation." (PMID 34150666, 2021). "We then cultured preOCs with the CM from coculturing MSCs with myeloma cells in the presence of anti-EGFR neutralizing antibody, and we observed less TRAP+ cells when EGFR were inhibited, indicating that myeloma cell-mediated osteoclastogenesis can be eased by deactivation of EGFR." (PMID 34150666, 2021). "In addition, multiple myeloma-derived epidermal growth factor receptor (EGFR) ligand amphiregulin-enriched exosomes were shown to promote EGFR pathway activation, inhibit osteoblast differentiation, and induce osteoclastogenesis." (PMID 32400849, 2020). "The dual ERBB2/EGFR inhibitor also effected majorly via EGFR pathway in myeloma cells." (PMID 25894462, 2015). "Addition of anti-EGFR antibody enhanced Alizarin red S staining in the cultures with the CM of MSCs cocultured with myeloma cells comparing to those with addition of IgG control, indicating that neutralizing EGFR reduced the inhibitory effect of myeloma cells on osteoblast differentiation." (PMID 34150666, 2021). "EGFR forms a complex with ALCAM in CNE-2R cells and primary multiple myeloma cells and RPMI8226 cells." (PMID 39594667, 2024). "To determine the effectiveness of our AEC approach in vivo, we transduced the multiple myeloma (MM) cell line U266 with retroviral vectors encoding truncated Her2 or EGFR, lacking the intracellular signaling domains (U266-tHer and U266-tEGFR) to rule out unwanted effects of Her2 or EGFR signaling." (PMID 37945970, 2024). "We have shown that anti-fluorescein CAR-T cells (FL-CAR-T cells) can target multiple antigens including EGFR, HER2, and CD38 expressed on the surface of the breast cancer, ovarian cancer, Burkitt lymphoma, and multiple myeloma cells." (PMID 36531912, 2022). "To further demonstrate the interaction between myeloma cells and MSCs through such complex, we transfected myeloma cells with His-tagged integrin α6 or transfected MSCs with GFP-tagged EGFR." (PMID 34150666, 2021). "The formation of a trimer complex among myeloma cell integrin α6, laminin 8, and EGFR on MSCs activates the Akt, ERK, STAT1/3 signaling pathways, and therefore upregulates osteolytic cytokine expression in both myeloma cells and MSCs." (PMID 34150666, 2021). "We report here a hybrid-capture-based Liquid Biopsy Sequencing (LB-Seq) method used to sequence all protein-coding exons of KRAS, NRAS, BRAF, EGFR and PIK3CA in 64 cfDNA specimens from 53 myeloma patients to >20,000 × median coverage." (PMID 28492226, 2017). "In this study, AREG enriched MM1.S multiple myeloma cell and multiple myeloma patient-derived bone marrow EVs promoted both RAW 246.7 and primary human CD14+ cell osteoclast differentiation, through EGFR activation, a 1.5-fold increase in MM9 protein expression and an increase in TRAP staining." (PMID 33143170, 2020).
type 2 diabetes (57 papers, 2013 to 2025). "A recent study has discovered a single nucleotide polymorphism (SNP) in an enhancer region within the EGFR gene that is linked to an increase in the expression of EGFR in individuals with type 2 diabetes." (PMID 40435181, 2025). "A recent study has also identified a SNP of an enhancer located in the EGFR gene associated with upregulation of EGFR expression in type II diabetes." (PMID 36359813, 2022). "A contribution of VSM-EGFR to obesity- and type 2 diabetes-associated and other vascular alterations, as well as enhanced vascular EGFR activity during hyperglycaemia with pathophysiological relevance, has been described." (PMID 32548701, 2020). "Inhibition of epidermal growth factor receptor activation is associated with improved diabetic nephropathy in type 2 diabetes." (PMID 33029194, 2020). "Several observations suggest a role for EGFR activation in vascular dysfunction associated with type 1 and type 2 diabetes." (PMID 24132149, 2013). "Furthermore, in vivo data revealed that treatment with cisplatin or metformin—a mitochondrial complex inhibitor and conventional therapy for type 2 diabetes—reduced IL-1RA-associated xenograft tumor growth as well as EGFR/JNK activation and SOX2 expression." (PMID 37461111, 2023). "It has been reported that metformin and EGFR-TKIs have a synergistic therapeutic effect in NSCLC patients with type 2 diabetes." (PMID 36969876, 2023). "Among them, the pathways of Type II diabetes mellitus, Legionellosis, Mitophagy, and EGFR tyrosinekinase inhibitor resistance were statistically significant (P value<0.05)." (PMID 36479123, 2022). "The role of ROCK as a downstream effector of EGFR/ErbB2 heterodimers was also confirmed recently in a mouse model of high-fat diet induced obesity/type 2 diabetes bearing vascular smooth muscle-specific deletion of EGFR." (PMID 34408653, 2021). "Oregano also significantly reversed the transcriptional effects of the anticancer drug BMS-690514 (a VEGFR and EGFR tyrosine kinase inhibitor), cocaine, and also of metformin, a drug used for the treatment of type 2 diabetes and of polycystic ovary syndrome." (PMID 33557421, 2021). "A retrospective study from our group showed that in advanced NSCLC patients with type 2 diabetes, metformin together with EGFR-TKI resulted in longer PFS and OS." (PMID 27144340, 2016). "The copy numbers of studies for risky genes in type-2 diabetes patients have shown that epidermal growth factor receptor (EGFR), E2F transcription factor 1 (E2F1), protein phosphatase 1 regulatory subunit 3A (PPP1R3A), human leukocyte antigen (HLA), and tetraspanin 8 (TSPAN8) are important." (PMID 34563047, 2021). "Additionally, EGFR signaling and ER stress are also reported to play a role in inducing myocardial infarction in type 2 diabetes." (PMID 34408653, 2021). "We show that VSM-EGFR mediates obesity/type 2 diabetes-induced vascular dysfunction, remodelling and transcriptome dysregulation preceding renal damage and identify an EGFR–glucose synergism in terms of SRF activation, matrix dysregulation and mitochondrial function." (PMID 32548701, 2020). "Thus, SRF represents a potential integration hub of EGFR and glucose-induced signalling during obesity/type 2 diabetes." (PMID 32548701, 2020). "Furthermore, the increased mesenteric and coronary arterial myogenic tone in a mouse model of type 2 diabetes was demonstrated to be clearly related to the elevation of EGFR protein expression and phosphorylation." (PMID 29360846, 2018). "Also, a retrospective study from our group showed that in advanced NSCLC patients with type 2 diabetes, metformin together with EGFR-TKI resulted in longer PFS and OS." (PMID 26497205, 2015). "EGFR phosphorylation is elevated in the type 2 diabetic mice (db/db)." (PMID 24132149, 2013). "In addition, previous reports indicated that EGFR TKIs may exert antidiabetic effects in type 1 and type 2 diabetes." (PMID 30735525, 2019).
type 2 diabetes (continued). "Furthermore, our data in rats and that from a mouse model of type 1 diabetes and in an experimental model of type 2 diabetes support the assertion that enhanced EGFR might be a common mechanism mediating vascular dysfunction in both type 1 and type 2 diabetes." (PMID 23826343, 2013). "We measured the soluble EGFR and adipsin levels in sera from 47 non-diabetic subjects and 106 subjects with type 2 diabetes using enzyme-linked immunosorbent assays (ELISAs) and analyzed the correlations between the soluble EGFR or adipsin levels and metabolic parameters in type 2 diabetes subjects." (PMID 33005239, 2020). "The role of VSM-EGFR during high-fat diet (HFD)-induced type 2 diabetes was investigated in a mouse model with inducible, VSM-specific EGFR-knockout (KO)." (PMID 32548701, 2020). "Given that metformin is safe, cheap and widely used to treat individuals with type 2 diabetes, obesity, and polycystic ovarian syndrome, we propose that metformin has potentially marked clinical utility in the future, since ILD events are an important consideration in the development of EGFR-TKIs." (PMID 26497205, 2015). "ARAP1, a susceptibility gene for type 2 diabetes, can regulate the endocytosis and ubiquitination of membrane receptors, but the effect of ARAP1 and its natural antisense long non‐coding RNA (lncRNA), ARAP1‐AS2, on the ubiquitination of EGFR in DN is not clear." (PMID 32969198, 2020).